FUNDC2 (FUN14 domain containing 2)
Diseases named in the same sentence as FUNDC2 in open-access papers:
FUNDC2 is named in the same sentence as 27 diseases in open-access papers, as found by Europe PMC text mining. Sharing a sentence is not in itself a finding about the gene and the disease. The quoted sentences say what the papers report.
cardiomyopathy (4 papers, 2022 to 2025). A disease of the heart muscle or myocardium proper. "The ablation of the FUNDC2 gene prevented DOX‐induced cardiomyopathy by ferroptosis and the knockdown of the SLC25A11 gene in FUNDC2‐KO cells significantly decreased mitoGSH levels and augmented erastin‐mediated ferroptosis." (PMID 40703196, 2025). "FUNDC2 knockout protects mice from DOX-induced cardiomyopathy by preventing ferroptosis, and SLC25A11 knockdown reduces mitoGSH to prevent erastin-induced ferroptosis in FUNDC2-KO cells." (PMID 39872359, 2022). "In DOX-induced cardiomyopathy, the FUN14 domain containing 2 (FUNDC2) protein at the OMM regulates mitochondrial GSH levels by influencing the stability of the mitochondrial glutathione transporter Solute Carrier Family 25 Member 11 (SLC25A11) and GPX4, thereby promoting ferroptosis." (PMID 40166597, 2025). "A study found that the mitochondrial outer membrane protein FUNDC2 promotes cell ferroptosis by regulating the stability of the SLC7A11 protein, thereby participating in the molecular mechanism of Doxorubicin-induced cardiomyopathy." (PMID 37152941, 2023). "Recently, it has been reported that FUNDC2 regulates ferroptosis by interacting with the mitochondrial glutathione transporter SLC25A11 to negatively regulate mitoGSH levels, and that it contributes to doxorubicin (DOX)-induced cardiomyopathy." (PMID 39872359, 2022).
breast carcinoma (3 papers, 2022 to 2025). "FUNDC2 was highly involved in various cancers especially breast cancers, phosphorylation modifications and structural changes also participate in anti-cancer therapy." (PMID 40294153, 2025). "In this study, we find that FUNDC2 expression in TNBC tissues is significantly higher than that in luminal subtype breast cancer tissues.FUNDC2 silencing in TNBC cells significantly reduces cell proliferation, migration and invasion." (PMID 37700593, 2023). "In the present study, we discovered a novel target, FUNDC2, by comparing luminal A subtype breast cancer and TNBC." (PMID 37700593, 2023). "Our results indicated that FUNDC2 expression in patients with triple-negative breast cancer was significantly higher than that in patients with luminal subtype breast cancer, and FUNDC2 expression was positively correlated with TNBC progression-free survival." (PMID 37700593, 2023). "The expression level of FUNDC2 in luminal breast cancer tissues was higher than the controls." (PMID 40294153, 2025). "The function of the outer mitochondrial membrane protein FUNDC2 in breast cancer is still unclear." (PMID 37700593, 2023). "Therefore, we focused our research on KCTD14 and FUNDC2, which might be novel targets in breast cancer, especially TNBC." (PMID 37700593, 2023). "Previous investigations involving breast cancer, HCC and cervical carcinoma demonstrated that FUNDC2 participated in cancers, supporting our findings that FUNDC2 also was involved in pan-cancer." (PMID 40294153, 2025). "The expressions of FUNDC2 and KCTD14 in luminal subtype breast cancer tissues and TNBC tissues were statistically different (P<0.05)." (PMID 37700593, 2023). "Our analysis revealed that there is a higher FUNDC2 expression in breast cancer tissues compared to the non-tumor controls, based on a cohort of 140 breast cancer cases, 33 non-tumor benign lesions, 82 non-TNBC cases, and 58 TNBC cases." (PMID 40294153, 2025). "There was a significant difference in the expression of FUNDC2 between breast cancer and nontumor benign lesions (P<0.05)." (PMID 37700593, 2023). "FUNDC2 has been reported in human hepatocellular carcinoma, but it is worth noting that the role of FUNDC2 in breast cancer and other tumor types has not been studied." (PMID 37700593, 2023). "Immunohistochemical EliVision method was used to detect the expressions of KCTD14 and FUNDC2 in 82 luminal subtype breast cancer tissues, 58 TNBC paraffin tissue samples and 33 nontumor benign lesions." (PMID 37700593, 2023). "FUNDC2 was negatively correlated with ER, PR and HER2 in breast cancer (P<0.05)." (PMID 37700593, 2023). "However, studies on FUNDC2 in breast cancer have not been reported thus far, and the potential mechanism by which FUNDC2 promotes the development of TNBC is still unclear." (PMID 37700593, 2023). "Moreover, in the case of control samples, we found overexpression of the proteins: PRDX2, PRDX5 and AIFM1 involved in ROS; TUSC2 in PMM; ALKBH7, RHOT1, SAMM50, IMMT and HSPA9 in the MMO; and FUNDC2 in MIT compared to luminal A and basal-like breast cancer tumors." (PMID 35327574, 2022).
hepatocellular carcinoma (3 papers, 2022 to 2025). A malignant tumor that arises from hepatocytes. "FUNDC2 overexpression was inversely correlated with the survival of the patients with hepatocellular carcinoma (HCC)." (PMID 40294153, 2025). "The authors demonstrate that elevated FUNDC2 causes mitochondrial fragmentation through inhibition of MFN1 in hepatocellular carcinoma and that knockdown of FUNDC2 inhibits liver tumorigenesis in mice." (PMID 35710796, 2022). "Here we report that a mitochondrial protein FUN14 domain containing 2 (FUNDC2) is transcriptionally upregulated in primary mouse liver tumors, and in approximately 40% of human hepatocellular carcinoma (HCC)." (PMID 35710796, 2022).
hemophilia A (2 papers, 2015 to 2020). The most common form of hemophilia characterized by spontaneous or prolonged hemorrhages due to factor VIII deficiency. "This is consistent with the absence of hemophilia A or moyamoya disease in the patient and also suggests a link between loss of function of FUNDC2 and CMC4 and the patient’s phenotype." (PMID 33193636, 2020). "Recently, an ~150 kb deletion of Xq28 encompassing part of F8, FUNDC2, CMC4, MTCP1, and BRCC3 was reported in a child with severe hemophilia A, Moyamoya disease, and distinctive facial features." (PMID 25927380, 2015). "However, it has been reported that an 18-year-old male carrying a deletion of the promoter and exon 1 of F8 and a large deletion/insertion that removes the entire coding sequence of FUNDC2 only showed severe hemophilia A but not HH." (PMID 33193636, 2020).
Moyamoya disease (2 papers, 2015 to 2020). Moyamoya disease (MMD) is a rare intracranial arteriopathy involving progressive stenosis of the cerebral vasculature located at the base of the brain causing transient ischemic attacks or strokes. "Deletions including FUNDC2, CMC4, MTCP1, and BRCC3 were reported in individuals with syndromic Moyamoya disease, characterized by angiopathy, short stature, and distinctive facial features." (PMID 25927380, 2015).
Cerebral ischemia (1 paper, 2024). Restriction of arterial blood supply to the brain associated with insufficient oxygenation to support the metabolic requirements of the tissue. "Furthermore, heightened expression of FUN14 Domain Containing 2 (FUNDC2) promotes mitochondrial transport of phosphatidylinositol-3,4,5-trisphosphate (PIP3), which modulates neuronal AkT/Foxo3a signaling in a model of cerebral ischemia/reperfusion, consequently increasing the expression of bim." (PMID 38962803, 2024).
cervical carcinoma (1 paper, 2025). A carcinoma arising from either the exocervical squamous epithelium or the endocervical glandular epithelium. "Additionally, FUNDC2 was also implicated in cervical cancer." (PMID 40294153, 2025).
diffuse large B-cell lymphoma (1 paper, 2025). "The mutation rate of FUNDC2 was the highest in diffuse large B-cell lymphoma 10.42% (> 10%), followed by stomach adenocarcinoma (> 5%)." (PMID 40294153, 2025).
Glucose intolerance (1 paper, 2022). Glucose intolerance (GI) can be defined as dysglycemia that comprises both prediabetes and diabetes. "In addition, it was found that liver-specific knockout of FUNDC2 promotes cellular accumulation of triglycerides and non-alcohol fatty liver disease (NAFLD), as well as glucose intolerance induced by high-fat diet in mice." (PMID 35710796, 2022).
invasive breast carcinoma (1 paper, 2020). A carcinoma that infiltrates the breast parenchyma. "DNASE1, FUNDC2, and IDS are genes hypermethylated in invasive breast cancer stage, although they demonstrate detectable hypomethylation in ADH and DCIS stages." (PMID 32051475, 2020).
triple-negative breast carcinoma (1 paper, 2023). An invasive breast carcinoma which is negative for expression of estrogen receptor (ER), progesterone receptor (PR), and human epidermal growth factor receptor 2 (HER2). "We preliminarily confirmed that the mitochondrial outer membrane protein FUNDC2 may promote the development of triple-negative breast cancer through the AKT/GSK3β/GLI1 signaling axis." (PMID 37700593, 2023).
cancer (4 papers, 2022 to 2025). A tumor composed of atypical neoplastic, often pleomorphic cells that invade other tissues. "The data in this study show clearly that the immune infiltration of the antigen-presenting cells especially the B cells is significantly associated with the expression levels of FUNDC2 in diverse cancers." (PMID 40294153, 2025). "Both phosphorylation sites and cancer mutation hotspots in FUNDC2 were further analyzed to uncover the potential overlapping amino acids." (PMID 40294153, 2025). "LASSO regression and univariate Cox analyses further validated the significance of FUNDC2 in cancer prognosis, emphasizing its potential as a diagnostic and prognostic marker." (PMID 40294153, 2025). "The possible association between FUNDC2 levels and immune infiltration of pan-cancer was explored by applying TIMER 2.0." (PMID 40294153, 2025). "The level of FUNDC2 was significantly associated with the survival of cancer patients." (PMID 40294153, 2025). "FUNDC2 mutation rates in cancer were relatively low (< 11%)." (PMID 40294153, 2025). "The observation that knockdown of FUNDC2 also reduces expression of AFP, an indicator of HCC malignancy, and a marker of cancer stem cells, suggests that the cancer stem cell compartment may be more susceptible to inhibition of FUNDC2." (PMID 35710796, 2022). "The data exhibited that mutation of Serine 167 in FUNDC2 to Lysine (Lys or K) or Proline (Pro or P) showed pathogenicity rates of 0.587 and 0.747, respectively, indicating that this site indeed plays a key role and also consistent with the clinical observations in cancer patients." (PMID 40294153, 2025). "Additionally, whether the mutations of FUNDC2 especially on the predicted phosphorylation sites are a cause or just a consequence in cancer remains to be explored." (PMID 40294153, 2025). "Secondly, a correlation between FUNDC2 expression and immune cell infiltration in cancers should be verified by experiments." (PMID 40294153, 2025). "The data show that there were significant differences in the expression levels of FUNDC2 between cancer tissues and controls." (PMID 40294153, 2025). "Second, diverse mutations of FUNDC2 including S167L, C96Y, and M139I are found in different cancer patients, as evidenced in the TCGA databases, suggesting that these variations of FUNDC2 at least are supported by clinical data." (PMID 40294153, 2025). "Collectively, these results indicate that FUNDC2 mRNA in normal tissues is higher than their respective cancer tissues." (PMID 40294153, 2025). "The expression of FUNDC2 was significantly correlated with immune infiltration of B cells and other immune cells in various cancers." (PMID 40294153, 2025). "Firstly, the relationship between FUNDC2 expression and patient outcomes across various cancer types should be addressed with more cases." (PMID 40294153, 2025). "Specifically, the levels of FUNDC2 in 8 cancers were significantly lower than the respective controls." (PMID 40294153, 2025). "The data in the current investigation show that the levels of FUNDC2 in cancer tissues were higher than those of controls generally." (PMID 40294153, 2025). "Future studies on FUNDC2 should include clinical analysis of FUNDC2 variations in patients with cancers and mice models." (PMID 40294153, 2025). "The possible relationship between FUNDC2 mRNA expression and prognosis of the patients with various cancers was studied by using GEPIA." (PMID 40294153, 2025). "Third, various variations of FUNDC2 are discovered in cancer patients, showing its potential diagnosis and treatment values." (PMID 40294153, 2025). "The mechanisms of why the expression levels of FUNDC2 affect the immune infiltration and the survival time of the patients with diverse cancers are studied." (PMID 40294153, 2025). "Collectively, the data demonstrate that FUNDC2 expression is involved in the prognosis of cancer patients possibly through its immune infiltration of various immune cells." (PMID 40294153, 2025).
cancer (continued). "TIMER 2.0, GEPIA, STRING, cBioPortal, and PhosphoNet databases were employed in this study to analyze the expression and prognostic role of FUNDC2 in pan-cancer, and the relationship between FUNDC2 expression and the degree of immune infiltration was examined." (PMID 40294153, 2025). "In a previous study, FUNDC2 gene overexpression was found in BC brain metastases; unfortunately, so far, there are few studies on this protein in cancer." (PMID 35327574, 2022). "Additionally, there are significant differences in the levels of FUNDC2 between different cancer tissues and the respective control tissues in most patients." (PMID 40294153, 2025). "The data demonstrated that there were significant differences between tumor tissues and their respective control tissues in 15 distinct cancers, of which the expression pattern of FUNDC2 mRNA in 8 tumor tissues was lower than the controls in most pan-cancers, especially BLCA." (PMID 40294153, 2025). "Expression of FUNDC2 in pan-cancer was investigated by employing TIMER 2.0." (PMID 40294153, 2025). "The biggest novelty of this study is that FUNDC2 is involved in most different types of cancers." (PMID 40294153, 2025). "Phosphorylation sites and variation of FUNDC2 overlapped, indicating that the S167L may be important in cancers." (PMID 40294153, 2025). "The expression of FUNDC2 in cancer tissues were lower than the normal tissues in most HCC samples." (PMID 40294153, 2025). "However, expression pattern and possible role and mechanism of FUNDC2 in pan-cancer remain to be investigated." (PMID 40294153, 2025). "FUNDC2 is a novel mitochondrial protein and is highly involved in various cancers." (PMID 40294153, 2025). "In conclusion, FUNDC2 may serve as a possible prognostic biomarker in pan-cancer and the mechanism may be involved in immune infiltration." (PMID 40294153, 2025). "The function of FUNDC2 in cancer, however, is poorly understood." (PMID 37700593, 2023). "Furthermore, reversal of mitochondrial fragmentation by FUNDC2 knockdown reduces tumor energy level, reprograms cancer metabolism, and suppresses primary liver tumors in an MFN1-dependent manner in vivo." (PMID 35710796, 2022). "Thus, it is possible that FUNDC2-induced mitochondrial fragmentation maintains cancer stem cells in HCC, which awaits further investigation." (PMID 35710796, 2022). "However, the possible role and mechanism of FUNDC2 in pan-cancer remains to be investigated." (PMID 40294153, 2025). "However, expression level and clinical significance of FUNDC2 in cancers remain to be investigated." (PMID 40294153, 2025). "Furthermore, variations of FUNDC2 in cancers were investigated by cBioPortal." (PMID 40294153, 2025). "Whether FUNDC2 regulates apoptosis of cancer cells could be further investigated in the future." (PMID 35710796, 2022). "Therefore, it is concluded that the expression level of FUNDC2 is highly related to the immune infiltration, and it is reasonable to deduce that the expression pattern of FUNDC2 can affect the immune infiltration levels of the immune cells in different cancer patients." (PMID 40294153, 2025). "It has been reported that the expression level of FUNDC2 is highly involved in TNBC and hepatocarcinoma by regulating cancer cell proliferation and invasion." (PMID 40294153, 2025).
tumor (4 papers, 2022 to 2025). "Specifically, the 167 serine mutation in FUNDC2 was discovered in tumor patients." (PMID 40294153, 2025). "Furthermore, FUNDC2 phosphorylation sites and tumor mutation hotspots should be analyzed in clinical investigations and mice models." (PMID 40294153, 2025). "Consistent with the pro-tumor roles of FUNDC2 in vivo, knockdown of FUNDC2 markedly reduced cellular colony formation on soft agar." (PMID 35710796, 2022). "Taken together, knockdown of FUNDC2 altered tumor cell metabolism and suppressed liver tumorigenesis in mice." (PMID 35710796, 2022). "Taken together, MFN1 is a critical downstream effector of FUNDC2 in reprogramming glucose and lipid metabolism in tumor cells." (PMID 35710796, 2022). "Taken together, inhibition of MFN1 is playing a critical role downstream of FUNDC2 in regulating mitochondrial fragmentation and respiration in tumor cells." (PMID 35710796, 2022). "FUNDC2 inhibited tumor growth in a subcutaneous tumorigenesis experiment in mice." (PMID 37700593, 2023). "Furthermore, pairwise comparison of tumor and para-tumor tissues revealed elevated FUNDC2 protein levels in 22 out of 54 HCC samples." (PMID 35710796, 2022). "In such a way, the robust tumor-promoting function of elevated FUNDC2 was revealed." (PMID 35710796, 2022). "Importantly, re-expression of FUNDC2 rescued tumorigenesis, indicating tumor suppression was due to specific ablation of FUNDC2." (PMID 35710796, 2022). "Thus, by inhibiting MFN1, FUNDC2 could promote tumor growth by metabolic reprogramming following dysregulated mitochondrial dynamics." (PMID 35710796, 2022). "Immunohistochemical analysis of FUNDC2 and GLI1 expressions in tumor tissues showed a positive correlation between them." (PMID 37700593, 2023). "There was a significant positive correlation between FUNDC2 and GLI1 in TNBC tumor tissues (R=0.552,P<0.001)." (PMID 37700593, 2023). "If inhibition of MFN1 is a key mechanism of tumor promotion by FUNDC2, overexpression of MFN1 should suppress tumorigenesis similar to FUNDC2 knockdown." (PMID 35710796, 2022). "Knockdown of FUNDC2 did not decrease the ratio of proliferating cells in tumor." (PMID 35710796, 2022).
genetic disorders (1 paper, 2020). "Our study provides novel insights into how loss of CMC4 and FUNDC2 contributes to dysregulation of apoptosis, inflammatory response, and HH and demonstrates the effectiveness of RNA-seq as a way to characterize gene function as part of understanding gene dosage in genetic disorders." (PMID 33193636, 2020).
FUNDC2 also shares sentences with these, for which no sentence is quoted: cataract (1 paper); Duodenal stenosis (1); gastric cancer (1); Gynecomastia (1); hemophilia (1); Hepatitis (1); Hypergonadotropic hypogonadism (1); infection (1); Klinefelter syndrome (1); metastatic cancer (1); pan (1); steatosis (1); stomach adenocarcinoma (1).